CD74 (CD74 molecule)
Diseases named in the same sentence as CD74 in open-access papers (continued):
Sharing a sentence is not in itself a finding about the gene and the disease.
fibrosis (3 papers, 2020 to 2023). the formation of excess fibrous connective tissue in an organ or tissue in a reparative or reactive process. "Mechanistically, Ltf interacts with CD74, which in turn represses the activation of mTORC1/S6K/eIF-4B axis to depress cardiac fibrosis after MI." (PMID 37351157, 2023). "Thus CD74+ ASCs may have a potentially important role in the treatment of radiation‐induced soft tissue fibrosis." (PMID 32563212, 2020). "In previous studies, we could show that MIF exerts direct inhibitory effects on HSC activation via the CD74/AMP kinase signaling pathway and that this function is a pivotal driver of its hepatoprotective effects in the hepatotoxin-induced fibrosis models." (PMID 33525493, 2021).
head and neck squamous cell carcinoma (3 papers, 2016 to 2024). A squamous cell carcinoma that arises from any of the following anatomic sites: lip and oral cavity, nasal cavity, paranasal sinuses, pharynx, larynx, and salivary glands. "CD74 was overexpressed in thyroid malignancy, malignant pleural mesothelioma, and head and neck squamous cell carcinomas, and it is associated with advanced tumor stage." (PMID 27323782, 2016). "In head and neck squamous cell carcinoma, CD74 expression is significantly increased during tumor progression." (PMID 39474111, 2024). "Interestingly, all five of these genes, CD74, C1QB, FCER1G, TYROBP, and C1QA are part of a protein-protein interaction network comprised of 20 proteins in total that are found only in head and neck squamous cell carcinomas but not in normal head and neck specimens." (PMID 31139325, 2019).
idiopathic pulmonary fibrosis (3 papers, 2023 to 2025). Idiopathic pulmonary fibrosis (IPF) is a nonneoplastic pulmonary disease that is characterized by the formation of scar tissue within the lungs in the absence of any known cause. "MIF has been suggested to be a key mediator that promotes fibrosis by activating CD74 in liver, renal and pulmonary fibrosis models." (PMID 41225611, 2025).
ischemic heart disease (3 papers, 2015 to 2025). "An increased expression of MIF and its ligand CD74 was also detected in the diabetic patients with coronary artery disease." (PMID 25661015, 2015).
kidney cancer (3 papers, 2015 to 2024). Primary or metastatic malignant neoplasm involving the kidney. "Studies of the role of MIF (which largely functions via the type II transmembrane receptor CD74) in prostate, bladder and kidney cancers suggested that it is a pro-tumorigenic factor in genitourinary malignancy." (PMID 39281682, 2024). "CD74 expression is increased during tissue injury in diverse organs and in malignancies, including kidney cancer." (PMID 26441987, 2015). "For kidney cancer, it was reported that the expression of CD74 is increased in diseased kidney and promotes an inflammatory response and may protect from interstitial kidney fibrosis." (PMID 36999961, 2023). "In summary, MIF-2 and MIF have an overlapping spectrum of activities mediated by CD74 activation and may cooperate, additively inducing chemokine secretion or survival in non-renal cells and proliferation in kidney cancer cells." (PMID 26441987, 2015).
malignant pleural mesothelioma (3 papers, 2016 to 2024). A malignant neoplasm that arises from mesothelial cells in the pleura and shows a diffuse growth pattern. "Our group recently identified the MIF-receptor CD74 as an independent prognostic factor for overall survival in patients with malignant pleural mesothelioma." (PMID 26883190, 2016).
mesothelioma (3 papers, 2016 to 2023). A usually malignant and aggressive neoplasm of the mesothelium which is often associated with exposure to asbestos. "Nevertheless, Otterstrom reported that high expression of CD74 was an independent prognostic factor for prolonged OS in mesothelioma pleural patients (low CD74: 8.2 months; medium CD74: 14.0 months; high CD74: 14.7 months; P < 0.001)." (PMID 37147569, 2023). "In vitro, reduction of MIF or CD74 levels in both mesothelioma cell lines showed that the MIF/CD74 signaling pathway promoted tumor cell proliferation and protected MPM cells from apoptosis." (PMID 26883190, 2016). "Human mesothelioma cells expressed more CD74 and secreted less MIF than non tumoral MeT5A cells, suggesting a higher sensitivity to MIF." (PMID 26883190, 2016). "In the present study, we compared the levels of expression of MIF and CD74 in different human mesothelioma cell lines and investigated their physiopathological functions in vitro and in vivo." (PMID 26883190, 2016). "All these data highlight the complexity of the MIF/CD74 signaling pathway in the development of mesothelioma." (PMID 26883190, 2016). "syngeneic implantations of murine mesothelioma cells deleted or not in MIF or CD74 expression into wild-type or MIF-deficient or CD74-deficient mice and study tumor development, tumor angiogenesis and identify the inflammatory cells recruited by the host." (PMID 26883190, 2016). "Finally, mesothelioma cell lines expressing high CD74 levels had a low tumorigenic potential after xenogeneic implantation in athymic nude mice." (PMID 26883190, 2016).
periodontitis (3 papers, 2024 to 2025). An acute or chronic inflammatory process that affects the tissues that surround and support the teeth. "Moreover, the upregulation of inflammatory cytokines such as CCL3 and immune response-related genes such as CD74 and HLA-DPB1 in cluster 5 suggests an enhanced immune response within the periodontal microenvironment as a hallmark of periodontitis-associated inflammation and tissue destruction." (PMID 38731950, 2024).
psoriatic arthritis (3 papers, 2025 to 2026). Joint inflammation associated with psoriasis. "The serum levels of anti-CD74 IgA antibodies were significantly higher in axSpA patients compared to control groups.73.3, 66.6 and 3.3% of the axSpA, Peripheral psoriatic arthritis and healthy group, respectively, were anti- CD74 IgA antibody positive." (PMID 41343024, 2025).
septic shock (3 papers, 2013 to 2020). Shock caused by infection; frequently caused by gram negative bacteria, although some cases have been caused by other bacteria, viruses, fungi, and protozoa; characterized by fever, chills, tachycardia, tachypnea, and hypotension. "In a cohort of 93 septic shock patients alive three days after shock, mHLA-DR was measured by flow cytometry and CD74, HLA-DRA, HLA-DMA, HLA-DMB and CIITA mRNA levels were evaluated in whole blood by qRT-PCR." (PMID 24321376, 2013).
skin cancer (3 papers, 2009 to 2024). "Bulk-RNA sequencing of patient tumor samples from the Skin Cancer SPORE Biorepository was used to evaluate for differential gene expression of MIF, DDT, CD74, and selected inflammatory markers, and gene expression was correlated with patient survival outcomes." (PMID 39028303, 2024). "In skin cancer models of WT, P1G-MIF, and MIF knockout mice revealed that the P1G-MIF group (lacking tautomerase activity and binding to CD74) displayed intermediate tumor incidence between the WT and knockout groups." (PMID 37880655, 2023).
squamous cell carcinoma (3 papers, 2022 to 2024). A carcinoma arising from squamous epithelial cells. "This study aimed to evaluate the gene and protein expressions of CD74 and HLA-DRA in the progression from normal cervix to precancerous cervical intraepithelial neoplasia (CIN) and finally to squamous cell carcinoma (SCC)." (PMID 35208514, 2022).
T cell lymphoma (3 papers, 2010 to 2023). "To determine if the mutant clones were specific to CD74, we measured the specific lysis on CD74 positive Mino cells (on-target signal) over a CD74 negative T cell lymphoma cell line SUDHL-1 (off-target noise) and compared the 3 mutant clones to the parent." (PMID 37740214, 2023). "To assess the sensitivity of MCL cells to 42105-74bbz CAR-T cells, we performed cytotoxicity assays in 6 CD74 positive MCL cell lines (JeKo-1, Mino, UPN-1, Granta-519, and Z138) and a CD74 negative T cell lymphoma cell line SUDHL1 as negative control." (PMID 37740214, 2023).
thyroiditis (3 papers, 2021 to 2024). Inflammation of the thyroid gland. "Thus, the interaction CD74/MIF in AITD could contribute to opposed processes: exacerbation of thyroid infiltration by immune cells (especially in HT) and promotion of autocrine TFC repair in GD, as demonstrated in IBD intestinal mucosa and in skin epithelium wound healing." (PMID 39003267, 2024).
type I diabetes (3 papers, 2021 to 2023). "The MIF/CD74 signaling pathway promotes macrophage-mediated inflammation in type 1 diabetes, and MIF controls the recruitment of inflammatory cells via chemokine receptors CXCR2 and CXCR4." (PMID 34445689, 2021).
acute lymphoblastic leukemia (2 papers, 2023 to 2025). Leukemia with an acute onset, characterized by the presence of lymphoblasts in the bone marrow and the peripheral blood. "In 2016, a study focused on adult and pediatric patients with B-cell acute lymphoblastic leukemia (B-ALL) revealed 29 in-frame fusion proteins, one of which was the novel CD74-PDGFRB." (PMID 37958963, 2023).
anaplastic large cell lymphoma (2 papers, 2021 to 2024). Anaplastic large cell lymphoma (ALCL) is a rare and aggressive peripheral T-cell non-Hodgkin lymphoma, belonging to the group of CD30-positive lymphoproliferative disorders, which affects lymph nodes and extranodal sites. "Furthermore, the involvement of CD74 can enhance the cytotoxic effects of traditional chemotherapy drugs on anaplastic large cell lymphoma (ALCL) cell lines." (PMID 39917362, 2024).
Arthritis (2 papers, 2019 to 2023). Inflammation of a joint. "Arthrogenic alphaviruses can cause debilitating illnesses characterized by arthritis and arthralgia, and evidence suggests that both MIF and CD74 play a critical role in mediating alphaviral disease." (PMID 30976033, 2019).
cardiac hypertrophy (2 papers, 2023 to 2025). "CD74_MIF, CD74_APP and CD74_COPA pairs were significantly enriched by B cells and macrophages at different stages of cardiac hypertrophy, indicating that CD74 played a crucial role in inflammation activity in cardiac hypertrophy." (PMID 36805782, 2023).
Cerebral ischemia (2 papers, 2020 to 2025). Restriction of arterial blood supply to the brain associated with insufficient oxygenation to support the metabolic requirements of the tissue. "In this study, we observed a marked upregulation of Cd74 in microglia following cerebral ischemia-reperfusion injury." (PMID 40400029, 2025). "Collectively, these findings suggest that targeted silencing of CD74 in microglia can mitigate brain injury following cerebral ischemia-reperfusion." (PMID 40400029, 2025). "This study provides strong evidence for the role of CD74 in microglia-mediated neuroinflammation following cerebral ischemia-reperfusion injury." (PMID 40400029, 2025).
cognitive decline (2 papers, 2011 to 2025). "In a meta-analysis of the two datasets, we find an increase in frequency of microglia with high CD74 expression (CD74high) in relation to AD dementia (p = 0.038), particularly in the phase of terminal, accelerated cognitive decline before death." (PMID 41282231, 2025). "Thus, CD74 staining helps us to resolve a distinct subset of microglia which is involved at the late, symptomatic phase of aging-related cognitive decline." (PMID 41282231, 2025). "Markers of neuroinflammation (e.g., CD74, GFAP) have been reported to increase in the hippocampus with age but the manner in which these changes may contribute to cognitive decline with normative aging remain to be determined." (PMID 21989322, 2011).
Crohn disease (2 papers, 2020 to 2023). A gastrointestinal disorder characterized by chronic inflammation involving all layers of the intestinal wall, noncaseating granulomas affecting the intestinal wall and regional lymph nodes, and transmural fibrosis. "CIITA, MHCII, and CD74 expression was significantly increased in IEC from Crohn’s disease (CD) patients with active disease compared to controls or CD patients in remission." (PMID 37818353, 2023).
cutaneous melanoma (2 papers, 2019 to 2020). A primary melanoma arising from atypical melanocytes in the skin. "In this study, survival analysis showed higher expression level of HLA class II co-expressed genes, especially APOL3, CD74, C1QA and C1QB, were associated with better prognosis in cutaneous melanoma." (PMID 31212865, 2019).
cystic kidneys (2 papers, 2022 to 2024). "Our results suggested that CD74 may be through regulating the expression of inflammatory factors to promote macrophage accumulation in cystic kidneys." (PMID 38534333, 2024).
depression (2 papers, 2023 to 2024). "Notably, a substantial number of upregulated genes associated with depression were identified, such as Ctss, Ifitm3, H2‐K1, Vim, Bst2, Lag3, Cd74, Isg15, Gbp3, and Cxcl10." (PMID 38946585, 2024).
dermatitis (2 papers, 2021 to 2025). An inflammatory process affecting the skin. "In a model of chemical skin injury and dermatitis, CD74 on invariant natural killer T (iNKT) cells interacted with MIF to promote iNKT cell migration to the skin." (PMID 33804792, 2021). "Related to dermatitis, we found an upregulation of CD74, BTLA, TRAF2, TNIP1, and IL19." (PMID 41416938, 2025).
diffuse large B-cell lymphoma (2 papers, 2024 to 2026). "Analysis of CD74 CNV and SNV showed markedly increased amplification of CD74 in KIRC and increased SNV rates in diffuse large B-cell lymphoma and UCS, although an increase in deep deletions was seen." (PMID 38582956, 2024).
endometrial cancer (2 papers, 2020 to 2025). Primary or metastatic malignant neoplasm involving the endometrium (mucous membrane that lines the endometrial cavity). "Our results identified CD74, HLA-DRB5, CD52, HLA-DPB1 and HLA-DRB1 as possible valuable genetic markers for the diagnosis and prognosis of endometrial cancer and provided a theoretical basis for immunotherapy targets for its clinical treatment." (PMID 33159014, 2020).
endothelial dysfunction (2 papers, 2022 to 2025). In vascular diseases, endothelial dysfunction is a systemic pathological state of the endothelium (the inner lining of blood vessels) and can be broadly defined as an imbalance between vasodilating and vasoconstricting substances produced by (or acting on) the endothelium. "These DORs were located at promoters of genes including CD74, IFI27, HLA-DMA, CASP8 and NOX4, which are associated with antigen presentation, inflammation and endothelial dysfunction." (PMID 41085167, 2025). "We identified promising new candidates to target endothelial dysfunction including CD74, the knockdown of which regulates EC proliferation and barrier integrity in vitro." (PMID 34528097, 2022).
Ewing sarcoma (2 papers, 2025). A small round cell tumor that lacks morphologic, immunohistochemical, and electron microscopic evidence of neuroectodermal differentiation. "MIF and the receptor CD74 can be used as a promising target to treat Ewing sarcoma, which is infiltrated by immunosuppressive myeloid populations." (PMID 40427533, 2025).
flu (2 papers, 2021 to 2024). "Influenza infection reduced CD74 and proSPC expression in mice lungs." (PMID 39201410, 2024).
HCMV infection (2 papers, 2020 to 2025). "Previous reports have indicated that latent HCMV infection in myeloid cells leads to an immunosuppressed profile characterised by high expression of B7-H4 or low expression of CD74." (PMID 40872823, 2025). "Taken together, these results indicate that the observed variation in CD74 cell-surface levels is induced following HCMV infection." (PMID 31967545, 2020). "An alternative option is that the differential expression of CD74 is driven by HCMV infection." (PMID 31967545, 2020).
Hepatitis (2 papers, 2022 to 2024). Inflammation of the liver. "From the health to hepatitis, the MIF signaling network and related ligand-receptor interactions, including MIF-(CD74 + CXCR4), MIF-(CD74 + CXCR2), and MIF-(CD74 + CD44) showed a significant effect on macrophage–naïve CD4 + T cell interaction." (PMID 36221095, 2022). "Additionally, we compared the differential expression of CD74 between alcohol vs. nonalcohol populations and between hepatitis-positive and hepatitis-negative populations in patients with HCC." (PMID 39118044, 2024). "Thus, the difference in predicting overall survival rate has little to do with CD74 levels in alcohol vs. nonalcohol or hepatitis-positive vs. hepatitis-negative populations." (PMID 39118044, 2024).
Hodgkins lymphoma (2 papers, 2013 to 2014). A heterogeneous group of malignant lymphoid neoplasms of B-cell origin characterized histologically by the presence of Hodgkin and Reed-Sternberg (HRS) cells in the vast majority of cases. "FISH and PCR analyses showed that these two Hodgkin lymphoma-derived hybrid tumors displayed both hamster and human DNA in the same nuclei by FISH, while also retaining the human genes, CD74, CXCR4, CD19, CD20, CD71, CD79b, and VIM." (PMID 25259521, 2014).
Hypertension (2 papers, 2020 to 2021). The presence of chronic increased pressure in the systemic arterial system. "Decreased expression of these RT1 genes, particularly Ba, CE3, CD74 and the Bb group, in the SHR would compromise AP signaling resulting in ineffective immune responses to gut dysbiosis and the altered luminal environment in hypertension." (PMID 34204247, 2021).
inflammatory diseases of skin (2 papers, 2018 to 2024). "While CD74 is overexpressed in skin inflammatory diseases and Fibroblast Activation Protein (FAP) is overexpressed in cutaneous cancers, implying a potential role of these markers in disease pathogenesis, isolating cells based solely on a single marker remains impossible." (PMID 39056788, 2024). "Further studies in indeterminate leprosy and paucibacillary leprosy, as well as other infectious and inflammatory diseases of skin, are required to describe the participation of MIF/CD74 in the immune response against leprosy in the skin." (PMID 29487601, 2018).
Interstitial pneumonitis (2 papers, 2022 to 2023). "Interestingly, overexpression of CD74 was also observed in samples of viral-mediated interstitial pneumonitis." (PMID 37124234, 2023).
ischemia (2 papers, 2012 to 2018). A hypoperfusion of the BLOOD through an organ or tissue caused by a PATHOLOGIC CONSTRICTION or obstruction of its BLOOD VESSELS, or an absence of BLOOD CIRCULATION. "Inhibition at this site could be problematic in cardiovascular diseases, as MIF/CD74 signaling conveys cardioprotection in early ischemia/reperfusion injury in the heart via activation of the tissue-protective AMP kinase pathway." (PMID 29581527, 2018). "CD74 expression did not change in the kidney in response to acute ischemia." (PMID 22253816, 2012).